IL6 (interleukin 6)
Diseases named in the same sentence as IL6 in open-access papers (continued):
Sharing a sentence is not in itself a finding about the gene and the disease.
cancer (continued). "Correlation analysis showed that the presence of terpinene, and likely eucalyptol, positively correlated with anti-cancer activity, while the presence of p-cymene and β-myrcene positively correlated with IL-6 expression, and camphor negatively correlated with IL-6." (PMID 36144796, 2022). "The increased and dysregulated activities of IL-6 can be found in cancer." (PMID 36547062, 2022). "IL-6 stimulates cancer cell proliferation, survival, and metastatic dissemination." (PMID 35954428, 2022). "Indeed, its overexpression is associated with increased BM and facilitates cancer cell transmigration across the BBB due to changes in breast cancer cell-secreted cytokines and chemokines such as IL-6, IL-8 and CCL5." (PMID 35884845, 2022). "Furthermore, to check the activity of azilsartan in both cancer cell lines at the molecular level, NF-kB/IL-6/JAK2/STAT3 signaling pathway was investigated." (PMID 36431925, 2022). "The expression of several fucosyltransferases involved in Lewis antigen synthesis in gastric cells has been shown to be modulated by the inflammatory cytokines, IL-1b and IL-6, and their prognostic effects on cancer and related motility mechanisms in cancer cells." (PMID 36292744, 2022). "Thus, these mutations are interesting targets for IL6-signaling targeted cancer therapy, which aims to block the activation of pathways downstream of IL-6 and reduce the proliferation and survival of cancer cells." (PMID 36547062, 2022). "Their differential responsiveness to IL-6 in terms of attraction of different monocyte subclasses suggests a different contribution of SM and LV fibroblasts to local and (potential) systemic inflammation in cancer, HF, and hereto related cachexia." (PMID 35967380, 2022). "Furthermore, primary macrophages secrete IL-6, which in turn increase IL-6 secretion from cancer cells, where IL-6 is shown to perpetuate this vicious cycle by generating more aggressive M2 macrophage polarization by activating Stat3 phosphorylation." (PMID 35960749, 2022). "The role of IL-6 in the progression of cachexia in patients with cancer was shown previously." (PMID 35954360, 2022). "Specifically, combination of resistance training with high-intensity aerobic training (60-min sessions, 2 days/week for 16 weeks) or resistance training per se (60-min sessions, 2 days/week, 12 weeks) mitigates and even counteracts cancer-mediated increased levels of IL-6." (PMID 35626116, 2022). "Meanwhile, our results indicated that the targeted inhibitor of IL-6 may augment the efficacy of anti-PD-L1 in NSCLC, paving the path for the utilization of IL-6 as a therapeutic target for cancer treatment." (PMID 35550592, 2022). "In addition, elevated serum concentrations of IL-6 correlate with worse prognosis in various cancers, including melanoma." (PMID 36015338, 2022). "Mechanistic studies showed that treatment of fibroblasts with viral product-containing exosomes promoted the characteristics of cancer-associated fibroblasts by stimulating YAP1 signaling and the production of the immunosuppressive cytokines IL8, CCL2, and IL6." (PMID 35986369, 2022). "Moreover, the IL-6 expression levels are significantly higher in the basal-like BC phenotype and in multi drug-resistant cancer cell lines." (PMID 35626741, 2022). "MDSCs expand peripherally in both cancer patients and tumor-bearing mice, at least in part driven by the systemic effects of cancer cell-derived cytokines that influence hematopoiesis in the bone marrow, including IL6 and CSF2." (PMID 36319998, 2022). "Furthermore, the induction of IL-6 by macrophages under hypoxic conditions enhances the metastatic and invasive capacity of cancer cells." (PMID 36497411, 2022). "Cross-talk between TGF-β and IL-6 has also been identified in drug resistance in some cancer cells." (PMID 35784460, 2022).
cancer (continued). "Under homeostatic conditions, IL-6 plays fundamental roles in immune response, inflammation, hematopoiesis, and bone homeostasis; however, dysregulation of IL-6 promotes the pathogenesis of multiple inflammatory and immune-mediated diseases, as well as, cancer." (PMID 35371975, 2022). "The IL-6/STAT3 signaling pathway is responsible for M2 polarization in cancer." (PMID 35193986, 2022). "IL‐6 is a pleiotropic cytokine and appears to play a dual role in cancer progression, which may depend on the duration of exposure." (PMID 35213038, 2022). "Additionally, IL-6 protects cancer cells from therapy-induced DNA damage, oxidative stress and apoptosis." (PMID 35884907, 2022). "IL-6 stimulates telomerase and miRNA cancer signaling in CCA cells." (PMID 35326593, 2022). "In addition, conophylline, an alkaloid isolated from Tabernaemontana divaricata, suppressed the pancreatic cancer desmoplasia and associated cytokines (IL-6, IL-8, CCL2, and CXCL12) produced by cancer-associated fibroblasts (CAF) and stellate cells." (PMID 36500466, 2022). "Additionally, the Western dietary pattern has been correlated with pro-inflammatory markers associated with cancer-related fatigue, including tumor necrosis factor (TNF)-α, C-reactive protein, interleukin (IL)-6, and IL-8." (PMID 35454890, 2022). "IL6 directly affects cancer dynamics, while IL10 and IL12 do it by affecting cytotoxic cells." (PMID 35294447, 2022). "The IL-6 signaling pathway is one of the most dysregulated pathways in cancer." (PMID 35371975, 2022). "NCTD affects iron metabolism by modifying the expression of IL-6/JAK2/STAT3/hepcidin and IRP1 and suggest that the ability of NCTD to reduce tissue iron contents may be a novel mechanism associated with the anti-cancer effects of NCTD." (PMID 35735222, 2022). "Combination of IL-6 signaling pathway inhibitor and other targets blockage drugs may serve as novel strategy to treat IL-6 mediated immune disease and human cancers." (PMID 35924148, 2022). "Thus, although IL-6 initially participates in the activation of the immune response, its prolonged, chronic release ultimately contributes to immunosuppression, severe cancer-related symptoms, and poor general patient status and prognosis." (PMID 35742933, 2022). "In metastasized cancer, high baseline levels of IL-6 and sCD40L are encountered." (PMID 36015440, 2022). "Various inflammatory biomarkers have been discussed in cancer studies as they have been linked to advanced cancer stages, resistance to immunotherapy, and poor prognosis: tumor necrosis factorα (TNF-α), interferon-γ (IFN-γ), and interleukin (IL)-1, IL-6, IL-8, IL-10, IL-11, and IL-17." (PMID 36499628, 2022). "Interleukin-6 (IL-6) is a keystone cytokine in inflammation and cancer, while its role in osimertinib efficacy was unknown." (PMID 35197546, 2022). "Thus, STAT3 transcriptional activity in cancer cells occurs at the level of IL-6-induced nanodroplets, which comprise phase-separated biomolecular condensates." (PMID 35406728, 2022). "In addition, lung CAFs secrete Cardiotrophin‐like cytokine factor 1 (CLCF1) and IL6, which stimulate the growth of cancer cells via the JAK/STAT signaling pathway." (PMID 35603909, 2022). "IL-6 is increasingly recognized as a key mediator of immunotoxicities in cancer patients receiving ICIs, and IL-6-targeted combination therapy might reduce adverse events." (PMID 35251033, 2022). "In addition, IL-6 diminishes the effects of anticancer treatments by facilitating DNA repair and inducing antioxidant and anti-apoptotic effects in cancer cells." (PMID 36015338, 2022). "IL-6 was significantly higher, contrasted by the non-cancer cohort (P< 0.05)." (PMID 36439504, 2022). "IL-6 is thought to be a key modulator linking inflammation with human fibrosis and cancer." (PMID 36465934, 2022). "Finally, CRP can lead to increased production of IL-6 and IL-8, which play a critical role in cancer cell metastasis." (PMID 35385679, 2022).
cancer (continued). "MDSCs are a heterogeneous population of immunosuppressive pro-tumoral leukocytes that result from abnormal myelopoiesis as a consequence, for example, of a pathological condition such as cancer that is accompanied by an increase in ROS, as well as IL-6, among other cytokines." (PMID 35562400, 2022). "The underlying mechanism is that inflammatory processes are involved in regulating the relationship between social support and cancer mortality, with patients at higher levels of social support and satisfaction having lower levels of inflammatory factors, including IL-6, TNF-α, CRP, and VEGF." (PMID 36091116, 2022). "IL-4 and IL-6 secreted by cancer cells could promote the infiltration and M2 polarization of macrophages." (PMID 35864548, 2022). "IL-6, a pleiotropic cytokine, plays a role in various cancers, including hematological malignancy." (PMID 36531024, 2022). "Some of the significant cancer hallmark terms are inflammatory response (CD14, CD69, IL10RA), KRAS signaling up (CD37, IL10RA, GPNMB), IL-6/JAK/STAT3 signaling (CD14, CSF2RB), Interferon Gamma Response (CD69, CSF2RB, IL10RA, VCAM1, SLAMF7), TNF-alpha Signaling via NF-kB (CD69)." (PMID 35486660, 2022). "A variety of signaling pathways including TNF-α, KRAS, IL-6/JAK/STAT3, IL-2/STAT5, epithelial-mesenchymal transition, oxidative phosphorylation, and mTOR were found to be significantly associated with TRPs in pan-cancer." (PMID 35831825, 2022). "Transcriptomic studies focusing on STAT3/IL-6 signaling at various stages of gastric disease and cancer could improve mechanistic understanding of this pathway’s role in carcinogenesis." (PMID 35757757, 2022). "As demonstrated by inhibition, IL6-dependent STAT3 signaling may involve SOCS3 upregulation in E3-ligase-dependent proteasome activation with cancer cachexia, as well as with denervation." (PMID 35626644, 2022). "The first major study to investigate IL-6 sequestrant use in the realm of cancer management was a phase II randomized trial involving the addition of siltuximab to bortezomib, melphalan, and prednisone (VMP) for newly diagnosed, transplant-ineligible multiple myeloma patients." (PMID 36031601, 2022). "Moreover, an SPHK1-driven NF-κB/IL-6/STAT3/S1PR1 amplification loop, was also essential for the development and progression of colitis-associated cancer." (PMID 36361531, 2022). "Moreover, TAMs support cancer stem cell expansion by producing several mediators, including IL-6 and platelet-derived growth factor (PDGF)." (PMID 36439180, 2022). "IL-6 overexpression was demonstrated in almost all cancer types." (PMID 35252204, 2022). "However, our result showed correlation presence destruction of periodontal tissue and cancer through Treg and IL-6 involved." (PMID 35804048, 2022). "IL-6 is a proinflammatory cytokine involved in cancer growth, invasion, progression and metastasis." (PMID 36713567, 2022). "IL-6 is one such example of a proinflammatory cytokine that orchestrates chronic inflammation, and has been connected to poor patient survival in different cancers." (PMID 35757000, 2022). "Stromal IL-6 inhibition of autophagy in cancer cells was confirmed in an animal model of CCA." (PMID 33925189, 2021). "Moreover, in mass spectrometry analysis performed on media collected from restimulated CD4+ T cells grown with cancer cells, the secreted cytokines and other factors such as IL-8, IL-6, CXCL1, and ICAM1 were found." (PMID 34439305, 2021). "Here, we aimed to validate with clinical and molecular data the hypothesis that CAF infiltration and release of IL-6 predict poor prognosis in CCA patients following dysregulation of autophagy in cancer cells." (PMID 33925189, 2021). "IL-6 also acts as an oxidative stress inducer in various cell types, particularly in cancer cells." (PMID 33513795, 2021). "Increased levels of IL6 have been observed in many cancers, especially OvCa." (PMID 34248988, 2021).
cancer (continued). "In addition, the potential of IL-6 in initiating VEGF expression has been shown in several cancer cells." (PMID 34206393, 2021). "Another cytokine found in the TME is IL-6, which plays important roles in cancer progression." (PMID 33758206, 2021). "The synthesis and activity of IL-6, though, is not limited to the cells of the cancer ecosystem." (PMID 34681685, 2021). "Moreover, CAF-secreted IL-6 acted in an autocrine fashion to drive the secretion of mir221/222-loaded microvesicles, which, in its turn, induced a stem-like phenotype in cancer cells." (PMID 34298736, 2021). "The blockade of IL-6 signaling through an antibody and the subsequent increase in cell radiosensitivity further confirmed the importance of this multifunctional cytokine for the survival of irradiated cancer cells." (PMID 34141616, 2021). "Similarly, IL-6 and IL-8 have been correlated with advanced stages of disease with unfavorable prognosis in many cancer." (PMID 34096454, 2021). "Therefore, despite strong experimental indications, the role of IL-6-mediated induction of STAT3 activity remains to be proven in cancer cachexia patients." (PMID 33419963, 2021). "HCC is a typical example of an inflammation related cancer where increased IL-6 and TNFα may be responsible for the activation of JAK/STAT3 signaling." (PMID 34639131, 2021). "IL-6 also promotes tumorigenesis by regulating multiple hallmarks of cancer and signaling pathways." (PMID 33510359, 2021). "Interleukin-6, one of the most studied cytokine involved in cardiovascular diseases and cancer progression, decreased significantly in cells exposed to EMPA/DOXO (12.4%, 21% and 49.5%, at 10, 50 and 500 nM, respectively, p < 0.001 for all), compared to cardiomyocytes exposed to DOXO alone." (PMID 34301253, 2021). "But IL-6 has been also described as a driver of tumorigenesis and high levels of circulating IL-6 concentrations are correlated with a poor prognosis and lower survival of cancer patients." (PMID 34671021, 2021). "However, detection is challenging in situ owing to low IL-6 serum concentrations, lower than 6 pg/mL in healthy humans and reaching elevated values of >80 pg/mL in cases of cancer or abnormal inflammation." (PMID 34443939, 2021). "In the present study, we show that the chemoattractant and activator of cancer cells is IL-6." (PMID 34440697, 2021). "Moreover, a study showed that treatment with CAF-derived IL-6 upregulated the expression of cancer stem cell markers and induced EMT transition, accompanied by increased migratory capacity in EAC cells." (PMID 33390169, 2021). "We aimed to validate with clinical and molecular data the hypothesis that CAF infiltration and release of IL-6 predict poor prognosis in CCA patients following dysregulation of autophagy in cancer cells." (PMID 33925189, 2021). "This is the first demonstration that the expression of IL-6 in the stroma and of autophagy markers in cancer cells may have prognostic value and help to stratify responder and not responder patients bearing a CCA." (PMID 33925189, 2021). "Furthermore, MSA treatment inhibited EGFR pathway and subsequntly reduced Interleukin-6 (IL-6) secretion in the supernatant of cancer cell lines." (PMID 34393797, 2021). "Transcriptional analyses of IL-6, RSAD2, IFIT1 and IFNB1 following treatment with the CPT analogue topotecan (Top) suggested that 15 and 21 out of 42 human cancer cell lines expressing STING showed increased IL-6 expression >2 fold after 6 and 24 h Top treatment, respectively." (PMID 35087822, 2021). "An interesting observation, confirmed both in animal models and in studies involving healthy adults, concerns the reduction in the gray matter area of the hippocampus, which shows an inverse relationship with the level of IL-6, which was also confirmed in studies on cancer patients." (PMID 34945157, 2021). "The blocking agents that combined with IL-6 and IL-6R may be potential anti-inflammatory drugs, and some of them may be anti-cancer agents." (PMID 33789615, 2021).
cancer (continued). "Likewise, it also imparts motility in cancer cells via NF-κB and IL-6 signaling and promotes EMT by facilitating the nuclear transport of the transcription factors SNAIL and β-catenin." (PMID 34588926, 2021). "Interleukin-6 (IL-6) is known to be involved in the pathogenesis of different cancers." (PMID 34582655, 2021). "Besides its pro-inflammatory functions, IL-6 also plays a crucial role in drug resistance in human cancer." (PMID 33816512, 2021). "We have verified that both the IL-6 and IL6R may be found on cancer cells from RCC patients with high IL-6." (PMID 32621022, 2021). "Once activated, NF-κB orchestrates the transcriptional responses of macrophages and other immune-competent cell types to trans-activate inflammatory gene products such as TNF, IL-6 and IL-22 which also play an important role in the cancer development and aggravation of CIA." (PMID 33842333, 2021). "Despite an altered host immune reactivity is frequently reported in cancer population, the increased IL-6 production by inflammatory and airway epithelial cells of smokers might be actively involved in the pathogenesis of such an aggressive immune response." (PMID 33216184, 2021). "Indeed, increased plasma levels of IL-6 generally negatively correlate with patient survival in many cancers." (PMID 33981307, 2021). "IL-6 is a pleiotropic cytokine that can enhance proliferation of cancer cells." (PMID 34669701, 2021). "Moreover, cancer cells produce cytokines via autocrine pathways, such as IL-6 and IL-8, which in turn induce CRP production." (PMID 33685417, 2021). "IL-6 plays an important role in modulating the immune response in cancer." (PMID 34441316, 2021). "Moreover, coculturing basal-like cancer cells with fibroblasts induced the expression of various interleukins and chemokines such as IL-6, IL-8, CXCL1, and CXCL3 and enhance metastasis through upregulating matrix metalloproteinase-9 (MMP-9)." (PMID 33916931, 2021). "Thus, several investigations point at a few signaling molecules/signaling pathways involved in the NSCLC stromal cancer cell crosstalk, including IL6, TGFβ, and CCL2." (PMID 34950592, 2021). "As IL-6 triggers PGRN expression in cancer studies 62, 63, IL-6 may serve as a crucial regulator of PGRN in response to microglial activation." (PMID 34400876, 2021). "The anti-inflammatory effect of skeletal muscle activity mediated by myokines (e.g., IL-6) could negatively contribute to the establishment of favorable inflammatory niche conditions, necessary for cancer metastasis." (PMID 33614663, 2021). "Interestingly, interleukin 6 (IL-6), a pro-inflammatory cytokine known to function upstream of progranulin in cancer progression, plays a critical role in early initiation of liver regeneration." (PMID 34681875, 2021). "Furthermore, IL-6 has been reported to be strongly expressed by ASCs and is a major player in the proliferation, migration, and invasion of some cancer cells." (PMID 34912237, 2021). "Similarly, previous studies have also demonstrated the presence of this IL-6/STAT3 feedback loop in other types of cancer." (PMID 34638305, 2021). "Our bioinformatic analysis was also aimed to investigate if epigenetic control through DNA methylation and miRNAs may be involved in IL-6 pathways regulation in cancer." (PMID 34576335, 2021). "Treatment with cisplatin increased TGF-β expression, and the conditioned media from cancer cells activated fibroblasts and increased their IL-6 production, concluding that IL-6 contribute to induce a paracrine loop that intercommunicated CAFs and NSCLS, resulting in chemoresistance." (PMID 34003341, 2021). "IL-6 plays a protective role for cancer cells, against DNA damage, apoptosis, and oxidative stress." (PMID 34440220, 2021).